AR (androgen receptor)
Diseases named in the same sentence as AR in open-access papers (continued):
Sharing a sentence is not in itself a finding about the gene and the disease.
prostate carcinoma (continued). "As AR signaling plays a key role along the disease of prostate cancer and ARSI has dramatically modified the natural history of this disease in different clinical settings, AR aberrations are still an essential target to inhibit during the continuum of care in prostate cancer." (PMID 36551557, 2022). "Gene fusion between androgen receptor (AR) response genes and E26 transformation-specific (ETS) family members increases the gene expression of ETS family members, and promotes tumorigenesis in prostate cancer." (PMID 36289913, 2022). "Curcumin and quercetin together restored AR protein levels in androgen-receptor negative prostate cancer cells." (PMID 36233012, 2022). "Prostate cancer development and progression have been heavily linked to Androgen Receptor (AR) signalling pathway; thus, androgen deprivation therapy (ADT) has been used for patients who have advanced prostate cancer." (PMID 35875638, 2022). "By revealing a novel role of TPX2 in the AR signaling pathway, the present study indicated that TPX2 may be an activator of AR and thus exhibits potential as a novel target for prostate carcinoma treatment." (PMID 35444697, 2022). "Based on our observation we think that it would be important to test combined AR- and NF-κB inhibition, probably including PI3K inhibitors, in preclinical prostate cancer models, and at a later stage also in clinical studies of metastasizing prostate cancer." (PMID 36551650, 2022). "We found that the PPIase inhibitor suppressed the proliferation of both androgen‐dependent (LNCaP) and androgen‐insensitive prostate cancer cells (LNCap AI), suggesting that the PPIase activity of FKBP51 is essential for cell proliferation in addition to AR regulation." (PMID 34057812, 2022). "In contrast to MCRPC, and consistent with other reports, in the present study the androgen receptor was found to be not expressed in canine prostate cancer tissues and cell lines." (PMID 35109825, 2022). "Prostate cancer (PC) can be kept in check by androgen deprivation therapy (ADT, usually with the androgen synthesis inhibitor abiraterone acetate or the androgen receptor antagonist such as enzalutamide) until the tumor evolves to castration-resistant prostate cancer (CRPC)." (PMID 36483309, 2022). "Finally, this work was primarily performed in the VCaP cell line, which contains wild-type full-length AR and demonstrates a unique responsiveness to both DHT and MDV compared to other prostate cancer cell lines." (PMID 35087237, 2022). "Inhibition of KDM6A/B with GSK-J4 has been shown to inhibit the proliferation of prostate cancer cell lines with castration-resistant prostate cancer cell lines, specifically those lacking the androgen receptor, exhibiting the highest sensitivity." (PMID 35915507, 2022). "The expression inhibition of ATAD2 intensely suppressed androgen-responsive or non-androgen-dependent AR-positive prostate cancer cell proliferation and led to a significant rise in tumor cell apoptosis." (PMID 36008934, 2022). "A very recent study showed that AR formed transcriptionally active condensates with coactivator MED1 in androgen-responsive prostate cancer cells such as VCaP and LAPC4 cells, but not in RWPE1, a normal prostate epithelial cell line." (PMID 35966880, 2022). "Considering the association of NAT10 expression with AR status and its alterations by AR modulators, there is a possibility that the activity of NAT10 could be involved in the castration treatment of prostate cancers." (PMID 35743017, 2022). "Furthermore, CCS1477, an inhibitor of p300/CBP bromodomain, inhibits proliferation and decreases AR- and C-MYC–regulated gene expression, modulated KLK3/PSA concentration, and has shown promise for the treatment of patients with advanced prostate cancer." (PMID 35704598, 2022).
prostate carcinoma (continued). "MALAT1, a long non-coding RNA often expressed and thought to deregulate RNA splicing in CRPC patients, was shown to be a regulator of androgen receptor expression, to mediate cancer cell growth, invasion and migration and to correlate with PSA values and Gleason grading in prostate cancer." (PMID 35159020, 2022). "This indicates that anti-inflammatory therapeutics given together with androgen receptor antagonists, and probably additional PI3K inhibitors, might have a beneficial effect for the therapy of metastasizing prostate cancer." (PMID 36551650, 2022). "In prostate cancer, downregulation of KDM5D is seen, thus enhancing expression of AR target genes." (PMID 35406676, 2022). "We did not have data about oral androgen receptor antagonists, which are rapidly becoming part of the standard of care for patients in earlier stage prostate cancer." (PMID 35804979, 2022). "Besides, the E3 ubiquitin ligase STUB1 is down-regulated in prostate cancer, leading to activated JMJD1A/AR signaling that enhances cancer progression and enzalutamide resistance." (PMID 36357379, 2022). "AR and MUC1-C have an inverse relationship in prostate cancer." (PMID 35154471, 2022). "In line with this concept, we previously reported that skeletal metastases from 10 different patients with prostate cancer harbored substantial fractions of AR-negative (ARNEG) prostate cancer cells and confirmed these findings at the transcriptional level." (PMID 36561929, 2022). "Androgen receptor (AR), a member of the nucleus receptor protein family (also known as nucleus receptor subfamily 3 group c member 4; NR3C4), plays a critical role in the transformation and proliferation of prostate carcinoma cells." (PMID 35444697, 2022). "Androgen receptor (AR)-castrate-resistant prostate cancer (CRPC) is an aggressive form of prostate cancer that does not have clinically approved targeted treatment options." (PMID 35453603, 2022). "Despite androgen dependence in a majority of castration-resistant prostate cancers, some cancer cells are independent of androgen receptor (AR) function, a feature of heterogeneity in prostate cancer." (PMID 35582526, 2022). "SHOT-RNAs are specifically expressed in estrogen receptor (ER)-positive breast cancer and androgen receptor (AR)-positive prostate cancer cells and are not expressed in other examined cancer cell lines." (PMID 35645336, 2022). "DNPC is a demanding subset of prostate cancer because there are no established specific therapeutic options, and the population has gradually increased since the introduction of next generation AR signaling pathway inhibitors." (PMID 36672609, 2022). "Data from a human AR positive prostate cancer cell line, LNCaP, reveals that the set of AR and CHD1 interacting proteins overlap considerably, and CHD1-bound enhancer regions are highly concurrent with those bound by the AR." (PMID 36212399, 2022). "In the absence of ARSI, this allows the AR cistrome to evolve and continue driving AR-dependent prostate cancer growth, while in the presence of ARSI this enables other transcription factors to rise in dominance and drive cancer progression." (PMID 36212399, 2022). "For example, the profiling of faecal microbiota reveals a difference in alpha diversity in gastrointestinal diversity of microbiota in men with versus those without prostate cancer and in men receiving oral androgen receptor axis-targeted therapies." (PMID 35158943, 2022). "As such, this study implicated storage of cholesteryl esters in LDs as an important process that supports AR-negative PC3 prostate cancer cell viability." (PMID 35033184, 2022).
prostate carcinoma (continued). "In summary, we found that in prostatic epithelial cells, androgen upregulates the transcription of ZFHX3 via the binding of AR to specific AREs in the ZFHX3 promoter, and the regulatory relationship between androgen/AR and ZFHX3 is valid in both mouse prostates and human prostate cancer specimens." (PMID 34953044, 2022). "Comparing PCa AR-cistrome to fibroblast AR-cistrome, the degree of overlap between the two cell types is greatly increased when FOXA1 is silenced in the epithelial prostate cancer cells, which suggests a role for FOXA1 in determining phenotypically epithelial specificity of AR signalling." (PMID 37435460, 2022). "We first confirmed that RM1 cells expressed AR and were growth inhibited by MeT and DHT, which collectively highlight the suitability of this model as a tool to understand the impact of potent androgen treatment on prostate cancer biology." (PMID 36923279, 2022). "As a result, concurrent treatment with the GSK3 inhibitor resulted in responsiveness of AR negative prostate cancer and ER negative breast cancer cells to inhibitors of the AR or ER, respectively, in in vitro and in vivo experimental models." (PMID 35402240, 2022). "Darolutamide is a novel AR antagonist approved for the treatment of non-metastatic castration-resistant prostate cancer." (PMID 36297536, 2022). "We next assessed the importance of the GalNAc-containing glycocalyx for prostate cancer cell motility and metastases in the absence of AR signaling." (PMID 35963852, 2022). "Based on our findings, it appears that TRIB2 induces lineage switching by developing stemness and NE characteristics, which supports enzalutamide-resistant prostate cancer cells in a way that they are no longer required to depend on AR-mediated signaling." (PMID 34973338, 2022). "In prostate cancer, the ERG protein also cooperates with the AR to influence disease progression." (PMID 36212399, 2022). "The TMPRSS2–ERG fusion is uniquely present in prostate cancer in approximately 50% of the cases; however, it does not occur upon lack of AR signaling." (PMID 35954292, 2022). "The lack of steady-state AR protein was required to maintain an AR negative, prostate cancer stem cell phenotype." (PMID 35328625, 2022). "Although agents targeting the androgen receptor (AR) improve the survival of individuals with hormone-dependent PC, most patients ultimately progress toward androgen receptor pathway-negative prostate cancer and further metastatic disease." (PMID 35406510, 2022). "Other TFs such as the Androgen receptor (AR) may activate, after androgen stimulation, prostate-specific RKIP expression in certain forms of prostate cancer." (PMID 36291854, 2022). "As an androgen receptor (AR) target gene with negative regulatory activity, DECR1 might support human prostate cancer (PCa) cell survival and resistance to AR targeting therapies." (PMID 36467089, 2022). "Darolutamide is an androgen receptor (AR) inhibitor that is approved for the treatment of non-metastatic castration-resistant prostate cancer." (PMID 36297536, 2022). "Enzalutamide is a nonsteroidal inhibitor of the androgen receptor (AR) signaling pathway and is used to treat patients with metastatic castration-resistant prostate cancer." (PMID 35740293, 2022). "Of note, EZH2 also contributes to the expression of AR transcriptional signatures in models of both primary prostate cancer and CRPC via a different mechanism that is independent of both PRC2 and its methyltransferase activity." (PMID 36212399, 2022). "In this study, we discovered that six cancer-specific cellular signaling pathways, the irinotecan pathway, metabolism, androgen receptor signaling, interferon signaling, MAPK/NF-kB signaling, and the tamoxifen pathway, were altered in the ETV4 subtype of prostate cancer." (PMID 36289913, 2022).
prostate carcinoma (continued). "Our findings of the gross overexpression of TRIB2 by enzalutamide treatment and the aggressive growth characteristics of TRIB2-OE cells signify a negative impact of AR blockade therapy for prostate cancer." (PMID 34973338, 2022). "Prostate cancer cells lacking AR are inherently refractory to AR-targeted therapies and can express IL1β at any stage of clinical progression." (PMID 36561929, 2022). "In another in vitro study, androgen receptor-positive prostate cancer cell lines did not trigger platelet aggregation." (PMID 35369325, 2022). "Furthermore, a study evaluating AR ChIP-sequencing of patient tissue (normal n = 4, localised n = 4, metastatic n = 3, and CRPC n = 3) identified that at every stage of prostate cancer, there is a distinct binding pattern for AR." (PMID 37435460, 2022). "To explore the underlying mechanisms of increased vertebral cancellous bone indices in Sirt1+/Δ vs. WT male mice, we sought to investigate the AR, as SIRT1 was previously reported to deacetylase and inhibit AR function in prostate cells in the context of prostate cancer." (PMID 36568088, 2022). "In advanced prostate cancer, IKBKE activity enhances AR levels via modulation of the Hippo pathway." (PMID 36035183, 2022). "It is, therefore, not surprising that the majority of prostate cancers (PCas) remain reliant on the AR signalling axis throughout their life." (PMID 35326402, 2022). "In summary, our results indicate that ivermectin suppressed the AR and E2F signaling pathways and DNA damage repair capacity by targeting FOXA1 and Ku70/Ku80 to inhibit cell proliferation and promote cell apoptosis in prostate cancer." (PMID 36050295, 2022). "Two human prostate cancer cell lines, PC-3 (androgen receptor negative) and 22Rv1 (androgen receptor positive), were used in the antiproliferative assay for all the obtained compounds." (PMID 36662205, 2022). "AR-mediated downregulation has been shown in prostate cancer cells when the AR is expressed in prostate cancer cells that do not usually express the receptor, but not in AR-expressing LNCaP cells." (PMID 35493092, 2022). "A recent study has also shown that the LIM domain only 2 (LMO2, a key regulator of hematopoietic stem cell development) is transcriptionally repressed by AR in prostate fibroblasts and that LMO2 is elevated in primary human prostate cancer vimentin+/αSMA+ CAFs in response to enzalutamide treatment." (PMID 36671452, 2022). "provided evidence to show AR as a direct substrate for the HAT activity of p300 and further identified that p300-mediated AR acetylation induces DHT-dependent AR transcriptional activity in cultured prostate cancer cells." (PMID 36060957, 2022). "Targeting important molecular ‘hubs’ where the Hippo, Notch and DDR pathways converge, such as the AR, ERG, AKT and TLK/NEK, may yield productive therapeutic approaches in prostate cancer." (PMID 35954292, 2022). "Although the investigated AR-dependent human prostate cancer cell lines (LNCaP and VCaP) vary a bit in their response to AR antagonists, both of them do not show any significant increase of cell death upon treatment." (PMID 36551650, 2022). "Similarly, for prostate cancer, KDM1A, BRD4, and PRMT1 were depleted in LNCaP cells as well as AR, FOXA1 and NCOA1, thus serving as positive controls." (PMID 35973998, 2022). "The AR degradation process through AhR activation was not identified in all types of prostate cancer cells." (PMID 36613955, 2022). "Evidence for functional interactions between BRCA1 and androgens was suggested by experiments showing differential regulation of the IGF1R gene by BRCA1 in androgen receptor (AR) positive, as compared to AR negative, prostate cancer cells." (PMID 35432218, 2022). "Thus, to model the AR/IL1β inverse correlation from patients with skeletal metastatic disease, we grafted GFP-expressing LNCaP prostate cancer cells directly into the tibiae of hormone-intact mice." (PMID 36561929, 2022).
prostate carcinoma (continued). "Although cell cycle processes were also predicted to be downregulated under these conditions, these data still support the notion that AR blockade fails to eliminate AR-dependent prostate cancer cells." (PMID 36551650, 2022). "AR protein expression has been found to be higher in GBM than in healthy brain tissue; the protein expression of this receptor increases with the malignancy of the glioma, which coincides with prostate cancer malignancy." (PMID 36361793, 2022). "To conclude, our study uncovered the prognostic value and carcinogenic role of USP13 in prostate cancer and showed that overexpression of USP13 may lead to activation of cancer-driving signaling pathways, such as PI3k, Wnt and AR." (PMID 36564767, 2022). "The standard treatment of metastasizing prostate cancer by androgen receptor blockers fails to provide a curative therapy, with most of the patients dying from tumor relapse." (PMID 36551650, 2022). "To investigate the oncogenic function of TR3 in prostate cancer, we analyzed its expression profile in prostate tumors (Gene Expression Omnibus database) and evaluated the correlation between TR3 and AR expression levels in prostate tumor patients (The Cancer Genome Atlas database)." (PMID 35454821, 2022). "Importantly, therapeutic strategies targeting the link between FOXA1 and the AR would be relevant in disease stages where AR signaling continues to be critical and where FOXA1 expression remains high, such as primary prostate cancer and CRPC." (PMID 36212399, 2022). "Prostate cancer has elevated 4-O-S CS content in the ECM, which may be due to inhibited androgen receptor (AR) signaling, thus resulting in increased 4-O-sulfotransferase CHST11 expression." (PMID 36433141, 2022). "Taken together, we identified a novel AR‐dependent lncRNA PCAL7 and PCAL7 may serve as a potentially therapeutic target against prostate cancer development." (PMID 33219721, 2021). "We identified that PCAL7 was highly expressed in AR‐dependent prostate cancer cell lines compared to AR‐less or ‐negative cells." (PMID 33219721, 2021). "In prostate cancer, for example, BMI1 (PCGF4) binds to the androgen receptor (AR) independently of the PRC1 complex thereby preventing protein degradation, which results in sustained AR signalling promoting tumour growth." (PMID 34316702, 2021). "Efficient AR antagonists, such as Enzalutamide and ARN-509, could be employed as potent anti-prostate carcinoma agents." (PMID 34568317, 2021). "Because androgen and AR play a fundamental role in the development of prostate cancer, TSPX might act as a modular for androgen and AR activities in the prostate." (PMID 33997036, 2021). "Despite significant improvements in clinical outcomes, prostate cancer in patients receiving next-generation AR therapies either fails to respond or ultimately develops resistance to the treatments." (PMID 34439133, 2021). "PC3 cells, on the other hand, are low-differentiated androgen-independent prostate cancer cells that do not contain endogenous AR." (PMID 34073059, 2021). "Together, these results strongly confirm the role of NMYC as a key master regulator toward AR-negative prostate cancer." (PMID 33420371, 2021). "We posit that the effects of androgens and androgen receptor signaling on TMPRSS2 and immune response could potentially contribute to the increased severity of COVID-19 in prostate cancer patients." (PMID 33915795, 2021). "Nrf-2 overexpression downregulated AR expression under basal conditions and decreased nuclear AR levels under DHT-stimulated conditions, and this effect was seen in both androgen-dependent (LNCaP) and androgen-independent (C4-2B) prostate cancer cell lines." (PMID 35582006, 2021). "We searched peer-reviewed literature on the PubMed database using key words “androgen-deprivation therapy,” “androgen receptor inhibitors,” “bone,” “bone complications,” and “nonmetastatic prostate cancer” from 2000 to present." (PMID 33028943, 2021).